DLGAP1-AS1 (DLGAP1 antisense RNA 1)
Synonyms: HsT914; FLJ35776
Gene: Long non-coding RNA gene on chromosome 18 (3,593,732 to 3,598,363, forward strand). Ensembl gene ENSG00000177337.
Diseases named in the same sentence as DLGAP1-AS1 in open-access papers:
DLGAP1-AS1 is named in the same sentence as 2 diseases in open-access papers, as found by Europe PMC text mining. Sharing a sentence is not in itself a finding about the gene and the disease. The quoted sentences say what the papers report.
glioma (1 paper, 2022). A benign or malignant brain and spinal cord tumor that arises from glial cells (astrocytes, oligodendrocytes, ependymal cells). "However, the biological function and mechanism of lncRNA DLGAP1 antisense RNA 1 (DLGAP1-AS1) in gliomas are still unknown." (PMID 35113786, 2022).
cancer (1 paper, 2021). A tumor composed of atypical neoplastic, often pleomorphic cells that invade other tissues. "One such oncogenic lncRNAs that has been reported in several cancers is the lncRNA DLGAP1 antisense RNA 1 (DLGAP1-AS1)." (PMID 33901010, 2021).